CCDC107 (coiled-coil domain containing 107)
Synonyms: PSEC0222; MGC31967
Tractability: Antibody: UniProt predicts a signal peptide or a membrane-spanning region; the Human Protein Atlas places it where antibodies can reach. PROTAC: ubiquitination databases record sites on it.
Gene: Protein-coding gene on chromosome 9 (35,658,290 to 35,661,511, forward strand). Ensembl gene ENSG00000159884.
Subcellular location: Membrane
Subcellular location (Human Protein Atlas): Cell Junctions; Plasma membrane; Nucleoplasm
Gene Ontology:
Molecular function: protein binding
Cellular component: membrane
Genetic constraint (gnomAD): Loss-of-function variants: 15 observed, 15.47 expected, observed/expected ratio (o/e) 0.97, 90% interval 0.65 to 1.49. The upper end of that interval is the gene's LOEUF score, 1.49, which puts it in group 6 of 6, group 1 being the genes least tolerant of losing a copy. Missense variants: 340 observed, 308.19 expected, observed/expected ratio (o/e) 1.1, 90% interval 1.01 to 1.21. Synonymous variants: 151 observed, 129.26 expected, observed/expected ratio (o/e) 1.17, 90% interval 1.02 to 1.34.
Homologues: Orthologues: chimpanzee CCDC107 (98% identical), macaque CCDC107 (90% identical), pig CCDC107 (69% identical), rabbit CCDC107 (65% identical), dog CCDC107 (63% identical), guinea pig CCDC107 (58% identical), mouse Ccdc107 (55% identical), rat Ccdc107 (52% identical).
Diseases named in the same sentence as CCDC107 in open-access papers:
CCDC107 is named in the same sentence as 5 diseases in open-access papers, as found by Europe PMC text mining. Sharing a sentence is not in itself a finding about the gene and the disease. The quoted sentences say what the papers report.
coronary artery disease (2 papers, 2020 to 2024). "CCDC97 and CCDC107 were found to be associated with coronary artery disease and diabetes-associated atherogenesis, respectively." (PMID 38540995, 2024).
glioblastoma (1 paper, 2025). The most malignant astrocytic tumor (WHO grade IV). "The network also includes CCDC107, which appears isolated with no direct interactions, implying that its role in glioblastoma remains unclear but may still be worth investigating given its potential involvement in cytoskeletal regulation." (PMID 40725410, 2025).
glioma (1 paper, 2025). A benign or malignant brain and spinal cord tumor that arises from glial cells (astrocytes, oligodendrocytes, ependymal cells). "CCDC103, a related protein, has been implicated in glioma progression and cytoskeletal organization, suggesting that CCDC107 may also impact tumor cell motility or structure." (PMID 40725410, 2025).
CCDC107 also shares sentences with these, for which no sentence is quoted: tumor (2 papers); diabetes (1).